GPR179 (G protein-coupled receptor 179)
Description:
Orphan receptor involved in vision. Required for signal transduction through retinal depolarizing bipolar cells. Acts as an atypical G protein-coupled receptor that recruits and regulates the R7 group RGS-GNB5 complexes instead of activating G proteins: promotes the GTPase activator activity of R7 RGS proteins, increasing the GTPase activity of G protein alpha subunits, thereby driving them into their inactive GDP-bound form (By similarity). Associates with components of metabotropic signaling cascade in retina ON-bipolar neurons, such as TRPM1 and GRM6: may control the ability of the GRM6 cascade to gate TRPM1 (By similarity).
Synonyms: GPR158L; GPR158L1; CSNB1E
Gene: Protein-coding gene on chromosome 17 (38,324,571 to 38,343,956, reverse strand). Ensembl gene ENSG00000277399.
Subcellular location: Cell membrane; Postsynaptic cell membrane; Cell projection, dendrite
Genetic constraint (gnomAD): Loss-of-function variants: 52 observed, 67.92 expected, observed/expected ratio (o/e) 0.77, 90% interval 0.61 to 0.96. The upper end of that interval is the gene's LOEUF score, 0.96, which puts it in group 4 of 6, group 1 being the genes least tolerant of losing a copy. Missense variants: 2,726 observed, 3,034.1 expected, observed/expected ratio (o/e) 0.9, 90% interval 0.87 to 0.93. Synonymous variants: 1,117 observed, 1,185 expected, observed/expected ratio (o/e) 0.94, 90% interval 0.9 to 0.99.
Homologues: Orthologues: chimpanzee GPR179 (99% identical), macaque GPR179 (93% identical), dog GPR179 (73% identical), pig GPR179 (73% identical), rabbit GPR179 (71% identical), rat Gpr179 (66% identical), mouse Gpr179 (65% identical), guinea pig GPR179 (59% identical), tropical clawed frog gpr179 (24% identical), zebrafish gpr179 (23% identical). Paralogues in human: GPR158 (19% identical).
Diseases named in the same sentence as GPR179 in open-access papers:
GPR179 is named in the same sentence as 14 diseases in open-access papers, as found by Europe PMC text mining. Sharing a sentence is not in itself a finding about the gene and the disease. The quoted sentences say what the papers report.
myopia (3 papers, 2022 to 2025). "Overall, these data demonstrate an impact of the loss of GPR179 upon the sensitivity to lens-induced myopia." (PMID 36613663, 2022). "We measured the retinal DA and DOPAC levels, the natural refractive development and the sensitivity to LIM induction in Gpr179−/− mice in order to improve our understanding of the role of cCSNB molecules and the ON signaling cascade upon retinal function and myopia onset and progression." (PMID 36613663, 2022). "Genes involved in the depolarization of ON bipolar cells include TRPM1, NYX, GPR179—detected in our described patient—and LRIT3, which, when damaged, similarly cause a negative ERG and are associated with high myopia." (PMID 40004769, 2025). "The aim of our study was to monitor whether the lack of GPR179 in a novel model of cCSNB has an impact upon DA turnover and induced-myopia." (PMID 36613663, 2022).
cystinuria (1 paper, 2023). Cystinuria is a renal tubular amino acid transport disorder characterized by recurrent formation of kidneys cystine stones. "Four additional variants were excluded because they were associated with a mild condition, including stationary night blindness (GPR179, MIM #614565), mild cystinuria (SLC7A9, MIM #220100), postaxial polydactyly (IQCE, MIM# 617642) and pseudoxanthoma elasticum (ABCC6, MIM #264800)." (PMID 36978159, 2023).
glaucoma (1 paper, 2021). Increased pressure in the eyeball due to obstruction of the outflow of aqueous humor. "Other variants in genes for IFT172, DFNB31, PDHX, SALL2, BMP4 and GPR179 by WES were excluded as deleterious and pathogenic mutations, and none of them was reported as a stronger/convincing glaucoma causing variant in the literature." (PMID 34399712, 2021).
Stickler syndrome (1 paper, 2024). Stickler syndrome is an inherited vitreoretinopathy characterized by the association of ocular signs with more or less complete forms of Pierre-Robin sequence, bone disorders, and sensorineural deafness (10% of cases). "Exome sequencing identified 21 potential pathogenic variants of 13 genes in 20 of 75 (26.7%) probands, including genes for Stickler syndrome (COL11A1 and COL2A1; 6/20), FEVR (FZD4, LRP5, and TSPAN12; 5/20), and others (FBN1, GPR179, ZEB2, PAX6, GPR143, OPN1LW, FRMD7, and CACNA1F; 9/20)." (PMID 38243264, 2024).
GPR179 also shares sentences with these, for which no sentence is quoted: congenital stationary night blindness (1 paper); infection (1); macular degeneration (1); night blindness (1); optic atrophy (1); polydactyly (1); Pseudoxanthoma elasticum (1); retinal degeneration (1); retinitis pigmentosa (1); Usher syndrome (1).